MIR668 (microRNA 668)
Synonyms: hsa-mir-668; MIRN668
Gene: MicroRNA gene on chromosome 14 (101,055,258 to 101,055,323, forward strand). Ensembl gene ENSG00000276352.
Gene Ontology:
Biological process: miRNA-mediated post-transcriptional gene silencing
Homologues: Orthologues: chimpanzee ptr-mir-668 (100% identical), mouse Mir668 (97% identical), guinea pig MIR668 (94% identical).